CCR2 (C-C motif chemokine receptor 2)
Diseases named in the same sentence as CCR2 in open-access papers (continued):
Sharing a sentence is not in itself a finding about the gene and the disease.
dry eye (4 papers, 2016 to 2024). "Other genes that were prevalently expressed, and associated with the pathogenesis of dry eye, included the chemokine receptor CCR2 and the T-cell chemoattractant, CCL5." (PMID 35562919, 2022). "The chemokine receptor CCR2 is highly expressed by T lymphocytes and monocytes/macrophages, with the latter being doubled in dry eye patients." (PMID 29673232, 2018). "This might explain the 2.61-fold increase of CCR2 mRNA in conjunctival imprints from dry eye patients." (PMID 29673232, 2018). "Indeed, animals with dry eye receiving CCR2 antagonist presented a decrease in corneal alterations and in pro-inflammatory cytokines TNF-α and IL-1β on the ocular surface, confirming the importance of CCL2 in the pathology." (PMID 27486749, 2016).
E. coli infection (4 papers, 2014 to 2025). "Using Ccr2+/− mice, which carry one functional Ccr2 allele and one RFP knock-in allele, which replaces the Ccr2 coding region, we also found that E. coli infection increased prostatic Ccr2+ cell abundance." (PMID 39748675, 2025). "TipDCs are recruited to the bladder via CCR2 during uropathogenic E. coli infection but are dispensable for bacterial clearance." (PMID 24945711, 2014).
esophageal squamous cell carcinoma (4 papers, 2021 to 2025). Esophageal squamous cell carcinoma (ESCC) is a type of esophageal carcinoma (EC) that can affect any part of the esophagus, but is usually located in the upper or middle third. "Paradoxically, increased expression of CCL2, a molecule that interacts with CCR2, has been linked to the accumulation of tumor-associated macrophages in esophageal squamous cell carcinoma (ESCC)." (PMID 38755605, 2024). "For example, the deletion of CCR2 in mice is associated with an increase in the CD8 T cells within the tumors in an N-nitrosomethylbenzylamine (NMBA)-induced esophageal squamous cell carcinoma (ESCC) model." (PMID 36429101, 2022).
fibrosarcoma (4 papers, 2020 to 2023). A malignant mesenchymal fibroblastic neoplasm affecting the soft tissue and bone. "In the murine MCA203 fibrosarcoma model, CCL2 was identified as a crucial chemokine recruiting MDSCs in the spleen in a CCR2-dependent manner." (PMID 37210553, 2023). "Additionally, the development of mechanical allodynia was blocked in neuropathic CCR2 knockout mice, and the treatment of DRG neurons in vitro with CCL2 obtained from fibrosarcoma culture supernatants increased the amount of mRNA for the Cavα2δ1 subunit." (PMID 34575835, 2021). "Furthermore, in fibrosarcoma (MCA) and mammary (PyMT) murine tumor models, the CCR2/CCL2 axis participates in the recruitment of Tregs from the lymph node to the tumor, as Ccr2-deficient Tregs were unable to infiltrate the TME." (PMID 33924428, 2021).
geographic atrophy (4 papers, 2011 to 2023). "For example, monocytes expressing CCR2 (C-C chemokine receptor type 2) have been found in the vicinity of geographic atrophy lesions, suggesting a pathogenic role." (PMID 37903056, 2023). "Up-regulation of Ccl2, Cxcl1, Cxcl10, and Cxcl11 are present in all forms of AMD, and the Ccl2/Ccr2 axis is implicated in the pathogenic accumulation of macrophages to the outer retina in models that feature aspects of either CNV or geographic atrophy, such as light damage." (PMID 26911327, 2016). "In summary, we have shown in this study that aged CCL2 or CCR2 deficient mice develop certain features of atrophic, but not angiogenic AMD-like changes, and as such, may represent an animal model for early stage human geographic atrophy." (PMID 21850237, 2011).
IgA nephropathy (4 papers, 2016 to 2023). "To explore the relationship between MCP-1 and CCR2 polymorphisms and IgA nephropathy (IgAN), we conducted this case-control study by enrolling 351 IgAN patients and 310 health controls." (PMID 27788494, 2016).
malignant pleural mesothelioma (4 papers, 2019 to 2023). A malignant neoplasm that arises from mesothelial cells in the pleura and shows a diffuse growth pattern. "CAR T cells engineered with CCR2 expression displayed satisfactory effector T-cell trafficking and antitumor efficacy in malignant pleural mesotheliomas and neuroblastoma tumors in mice." (PMID 33381115, 2020). "In another study, C-C motif chemokine receptor 2 (CCR2) on CAR-T cells was modified to target the cognate chemokine CCL2, which is highly expressed in malignant pleural mesothelioma." (PMID 36979400, 2023).
metastatic cancer (4 papers, 2015 to 2022). A carcinoma which has spread from the original site of growth to another anatomic site. "Nevertheless, an anti-CCR2 antibody (MLN1202) tested in a phase II clinical trial for metastatic cancer showed therapeutic effects in 14 out of 43 patients with bone metastases (ClinicalTrials.gov ID: NCT01015560)." (PMID 26275794, 2015). "Besides, macrophage infiltration has be stunted after blocking the binding of MCP-1 to monocytes expressing the receptor of CCL2 (CCR2), which let mice to delay the progression of metastatic cancer and extend survival." (PMID 28207826, 2017). "Although the interest in CCL2-CCR2 signaling was increased in recent years, mostly due to its relation to solid and metastatic cancers, CCR2 chemokine was not analyzed in AMD patients despite mediating not only a pro-tumorigenic function but also angiogenesis." (PMID 35888126, 2022).
migraine (4 papers, 2013 to 2024). "According to previous clinical research, a high level of MCP-1/CCL2 was observed in the serum of patients with migraine; moreover, CCR2 was also associated with migraine." (PMID 37450927, 2024). "High levels of monocyte chemoattractant protein-1 (MCP-1; also known as chemokine receptor type 2, CCR2) are associated with meningeal neuroinflammation in migraine." (PMID 23326332, 2013). "DNA samples from 103 subjects with migraine and 100 healthy subjects were analyzed for CCR2 gene polymorphism." (PMID 24453913, 2013). "There is only one study about migraine and CCR2V64Il which revealed an association between migraine and CCR2 but the association did not remain after adjustment for multiple testing." (PMID 24453913, 2013).
oral cancer (4 papers, 2022 to 2024). "In conclusion, oral cancer stroma–secreted CCL2 is a key signal for recruiting CCR2+ MDSCs from BM to the TME." (PMID 34874922, 2022). "CAFs can also release CCL2, leading to the recruitment of CCR2 + MDSCs into oral cancer." (PMID 37221555, 2023). "We further examined the expression of CCR4, CXCR3, P2RY14, CCR2, CCR8, and CCL19 in highly aggressive oral cancer cell lines and tissues." (PMID 38213736, 2024). "The expression of CCR4, CXCR3, CCR2, and CCR8 was higher in highly invasive oral cancer cell lines (SCC-25, CAL-27, and FaDu) than in the less aggressive cell line (HSC-2), whereas CCL19 and P2RY14 expression showed the opposite trend." (PMID 38213736, 2024). "CCL2/CCR2 and intercellular adhesion molecule-1 (ICAM-1) are other important pathways that stimulate the recruitment of TAMs into oral cancers." (PMID 37221555, 2023). "Specifically, these findings indicate that CCR4, CXCR3, CCR2, and CCR8 may affect the invasiveness of oral cancer cells." (PMID 38213736, 2024). "Suppression of chemoattracts such as CCL2/CCR2 and EGFR may be intriguing for oral cancer therapy." (PMID 37221555, 2023). "Further analysis of gene expression in clinical tissues revealed that CCR4, CXCR3, CCR2, and CCR8 exhibited higher expression in oral cancer cells of patients with metastasis compared to those without, whereas CCL19 and P2RY14 displayed the opposite trend." (PMID 38213736, 2024).
oral squamous cell carcinoma (4 papers, 2020 to 2026). "The CCL2/CCR2 signaling axis offers a new research direction for treating oral squamous cell carcinoma." (PMID 42038362, 2026). "Increasing KIF4A can promote the recruitment of macrophages toward oral squamous cell carcinoma cells and educate them to M2 polarized macrophages through regulating CCL2/CCR2." (PMID 33101367, 2020).
pancreatitis (4 papers, 2018 to 2023). Inflammation of the pancreas. "We depleted either neutrophils with an anti-Ly6g antibody or monocytes via anti-CCR2 antibody 1d before and 1d after onset of pancreatitis." (PMID 36300116, 2022). "For example, CCL2 produced by acinar cells leads to the development of pancreatitis via migration of CCR2-expressing myeloid cells into the pancreas." (PMID 29891873, 2018). "To evaluate the local pancreatic immune response during pancreatitis, we labelled tissue sections with CD68 and CCR2 to identify pancreatic macrophages and infiltrating monocytes." (PMID 37402858, 2023).
pneumococcal infection (4 papers, 2017 to 2022). Infections with bacteria of the species streptococcus pneumoniae. "With pneumococcal infection, CCR2 mediates the initial recruitment of Ly6C+ monocytes, but neither AM numbers nor phenotypes in the recovered lung depended upon this chemokine receptor." (PMID 35133985, 2022). "In comparison, the CCR2−/− mice had unaltered lung neutrophils infiltration during the pneumococcal infection." (PMID 34512626, 2021). "To investigate whether CCR2 also directs tissue-infiltrating γδT17 cells during infection, we used experimental Streptococcus pneumoniae infection, immunity to which requires γδT17 cells." (PMID 28580944, 2017). "In another context, the CCR2− subpopulation within the meninges rather than CCR2+ cells predominantly controls Streptococcus pneumoniae infection in the CNS." (PMID 27723233, 2017).
pneumonitis (4 papers, 2007 to 2024). An inflammatory process affecting the lung parenchyma. "In contrast, transfer of CCR2-Treg cells, even in smaller numbers, ameliorated the progression of both pneumonitis and sialadenitis." (PMID 17284325, 2007). "Cultured Treg cells and CCR2-Treg cells were transferred via retro-orbital injection into 12-week-old MRL/lpr mice (at the early stage of pneumonitis and sialadenitis)." (PMID 17284325, 2007). "In the present study, we prepared CCR2-expressing Treg cells and demonstrated their ability to ameliorate pneumonitis and sialadenitis in MRL/lpr mice by accumulating in target organs." (PMID 17284325, 2007). "MRL/lpr mice to which CCR2-Treg cells had been transferred showed significantly reduced progression of pneumonitis and sialadenitis in comparison with MRL/lpr mice that had received Treg cells." (PMID 17284325, 2007). "Therefore, MRL/lpr mice that had undergone transfer of CCR2-Treg cells showed significant amelioration of pneumonitis and sialadenitis progression in comparison with CD4+CD25- CCR2-transferred MRL/lpr mice." (PMID 17284325, 2007). "CD4+CD25+Foxp3+ T cells (Treg cells) and CD4+CD25+Foxp3+ CCR2-transfected T cells (CCR2-Treg cells) were transferred via retro-orbital injection into 12-week-old MRL/lpr mice at the early stage of pneumonitis and sialadenitis, and the pathological changes were evaluated." (PMID 17284325, 2007). "Then, we characterized the CCR2-expressing CD4+CD25+ regulatory T cells and their therapeutic effect on sialadenitis and pneumonitis by accumulating them in target organs in MRL/lpr mice." (PMID 17284325, 2007). "On the basis of these results, we investigated whether pneumonitis and sialadenitis in MRL/lpr mice could be ameliorated by accumulation of CCR2-expressing CD4+CD25+ regulatory T cells in target organs." (PMID 17284325, 2007).
renal carcinoma (4 papers, 2016 to 2024). A carcinoma arising from the epithelium of the renal parenchyma or the renal pelvis. "While the density of CD68+ TAMs was similar in primary renal cancer and brain metastases, the CCR2-positive TAMs (proinflammatory type) were more frequently expressed in brain metastases than in primary renal cancer." (PMID 36527157, 2022). "We thus investigated the influence of kahweol acetate and cafestol on C–C chemokine receptors (CCR2, 5, and 6) of representative chemokines activating renal cancer cells." (PMID 33436830, 2021). "Thus, the blockade of the CCL2/CCR2 signaling pathway to treat renal cancer is a promising direction and deserves further investigation." (PMID 27409666, 2016).
renal cell carcinoma (4 papers, 2016 to 2025). "BMS-813160, a dual CCR2/CCR5 antagonist, was investigated with nivolumab for advanced renal cell carcinoma to change TAMs and improve anti-PD-1 efficacy in a phase 2 clinical trial, NCT02996110." (PMID 40422244, 2025). "CCR2 is the specific receptor of MCP-1, and the MCP-1/CCR2 signal axis was involved in the transmission of cell information and cell migration, which could enhance cell proliferation and migration ability of renal cell carcinoma by autocrine." (PMID 27788494, 2016).
sarcoma (4 papers, 2011 to 2025). A usually aggressive malignant neoplasm of the soft tissue or bone. "Monocytes are regulated by CCR2 in the tumor immune microenvironment of sarcoma." (PMID 38564630, 2024). "SQLE expression was negatively correlated with the expression of chemokines (CCL19 and CX3CL1) and chemokine receptors (CCR2 and CCR7) in sarcoma." (PMID 38335381, 2024).
subarachnoid hemorrhage (4 papers, 2022 to 2024). A serious neurological disorder characterized by intracranial hemorrhage into the subarachnoid space. "The inhibition of CCR2 has been shown to alleviate neuroinflammation and neuronal apoptosis following subarachnoid hemorrhage through the PI3K/AKT pathway." (PMID 39193227, 2024). "Accumulation of macrophages positive for CCR2 and CX3CR1 was found in all periods after subarachnoid hemorrhage as well as after the application of artificial cerebrospinal fluid." (PMID 39839349, 2024).
systemic sclerosis (4 papers, 2013 to 2023). A chronic disorder, possibly autoimmune, marked by excessive production of collagen which results in hardening and thickening of body tissues. "The lower percentage of CCR2+Tfh in the patients could indicate CCL2-directed migration of such cells into lymphoid tissues and/or target organs in systemic sclerosis." (PMID 33407866, 2021).
alcohol (3 papers, 2018 to 2021). "Chronic alcohol also induced cytokine expression and microglial activation that was partially normalized by CCR2/5 inhibition." (PMID 33036616, 2020).
anemia (3 papers, 2023 to 2025). A reduction in the number of red blood cells, the amount of hemoglobin, and/or the volume of packed red blood cells. "Ly6C/CCR2-expressing macrophages are observed in the spleens of mice with acute anemia and stress erythropoiesis, but then lose the expression of these cell surface markers as they mature." (PMID 37495396, 2023). "Furthermore, multivariate Cox regression analysis identified postoperative CCR2–4, PCI > 20, and tumor grade 3–4 as the independent risk factors for postoperative OS in the normal Hb group and all anemia subgroups (all P < 0.05)." (PMID 41341392, 2025). "Moreover, PF-04136309 is a CCR2 inhibitor that targets tumor-associated macrophages, and a phase 1b trial revealed that PF-04136309 in combination with FOLFIRINOX chemotherapy decreases the incidence of grade III anemia (8%) in pancreatic cancer compared with FOLFIRINOX alone." (PMID 37208766, 2023). "Combining potential cancer-induced anemia therapeutic targets, such as TGF-β, VEGF signaling, hepcidin, IL-6, CD71, CCL2/CCR2, GM-CSF, and exercise, with ICIs could therefore be an effective therapeutic approach." (PMID 37208766, 2023).
Arrhythmia (3 papers, 2024 to 2025). Any cardiac rhythm other than the normal sinus rhythm. "HSPA6 mutations affected domains essential for ATPase activity, potentially impairing stress response functions —particularly relevant given its correlation with CCR2 in arrhythmia-associated macrophages." (PMID 40900730, 2025). "Consistent with diminished arrhythmogenic substrate(s) in Dsg2mut/mut × Ccr2–/– and Dsg2mut/mut × IκBαΔN mice, infusion of dobutamine (a β1-adrenergic agonist) and caffeine at 16 weeks of age resulted in fewer induced arrhythmias compared with Dsg2mut/mut mice." (PMID 38564300, 2024).
Cachexia (3 papers, 2020 to 2026). Severe weight loss, wasting of muscle, loss of appetite, and general debility related to a chronic disease. "Ccr2 deletion resulted in even greater attenuation in cachexia and immune cell infiltration into the brain." (PMID 32391790, 2020). "To identify unique mechanisms of immune cell recruitment to the brain and determine if inhibiting immune cells from infiltrating the brain attenuates cachexia, we treated OT-implanted tumor-bearing mice with either a CCR2 inhibitor (RS504393, Tocris) or CXCR2 inhibitor (SB225002, Tocris)." (PMID 32391790, 2020). "It should be noted that both RS504393 and SB225002 treatment resulted in a nonsignificant decrease in neutrophils in the VI, yet only RS504393 treatment decreased cachexia, suggesting that monocytes (since CCR2 is typically important in monocyte chemotaxis) may be important mediators of cachexia." (PMID 32391790, 2020). "This suggests that a drug targeting CCR2 could help to reduce the symptoms of cachexia, without disrupting the normal immune response away from the brain." (PMID 32391790, 2020).
Candida infection (3 papers, 2014 to 2025). "Depleting CCR2+ cells interrupts monocyte infiltration and increases fungal burdens in kidney, brain, and spleen during early phase of Candida infection." (PMID 28217127, 2017).
cerebral infarction (3 papers, 2020 to 2023). An ischemic condition of the brain, producing a persistent focal neurological deficit in the area of distribution of the cerebral arteries. "Compared with that in wild-type mice, CCR2-deficient mice had a small cerebral infarction size after ischemia–reperfusion, which reduced BBB permeability as well as inflammatory cytokine expression." (PMID 36566220, 2022). "However, in chronic IS, CCR2+ monocytes could reduce the acute brain infarct volume and brain swelling and improve functional recovery." (PMID 37508983, 2023). "Further, studies have demonstrated that the genetic deletion of CCL2 and CCR2 reduced the permeability of the BBB, the accumulation of immune cells in ischemic brain tissues, and subsequent cerebral infarction." (PMID 32872405, 2020).
chondropathy (3 papers, 2017 to 2024). "Regarding the similar role of CCL2 in the pathogenesis of RA and OA, CCN1 inhibition could serve as a potential strategy via reducing the CCL2/CCR2 axis-mediated inflammation in these bone and cartilage disorders." (PMID 39076996, 2024). "In agreement with previously published studies, we found that although chondropathy scores were not affected by Ccr2 deletion, there was a change in the course of pain-related behaviour following DMM." (PMID 27746376, 2017).
chronic obstructive pulmonary disease (3 papers, 2021 to 2024). A chronic and progressive lung disorder characterized by the loss of elasticity of the bronchial tree and the air sacs, destruction of the air sacs wall, thickening of the bronchial wall, and mucous accumulation in the bronchial tree. "64Cu-labelled ECL1i was used in a murine model of lung inflammation and in human biopsies from patients with chronic obstructive pulmonary disease (COPD) to visualize CCR2+ cells in both species." (PMID 33669804, 2021). "In the following year, the same group used 1 to characterize CCR2 in mouse models of lung injury (PET study) and in human tissues (autoradiography study) from subjects with severe chronic obstructive pulmonary disease (COPD)." (PMID 34500609, 2021).
co-infection (3 papers, 2017 to 2026). "Recruitment of F4/80low MΦ in response to SL3261 was ablated in Ccr2-/- animals both in single and co-infection whereas expansion of resident F4/80high MΦ was unaltered during H. polygyrus infection." (PMID 28334040, 2017). "Our observation of increased CCR2 expression on monocytes from PWH with a positive TST/IGRA may inform future CCR2 immunomodulatory trials, particularly for areas where HIV/Mtb coinfection is prevalent." (PMID 41488698, 2026).